KHK (ketohexokinase)
Description:
Catalyzes the phosphorylation of the ketose sugar fructose to fructose-1-phosphate.
Synonyms: FRUCTU
Tractability: Small molecule: a structure with a bound ligand is known; a high-quality ligand is known; it has a high-quality binding pocket; it belongs to a druggable protein family. PROTAC: ubiquitination databases record sites on it; a small molecule that binds it is known.
Target class: Enzyme; Transferase
Chemical probes: BI-9787 (high quality), KHK-IN-1 (high quality), PF-06835919 (high quality)
Gene: Protein-coding gene on chromosome 2 (27,086,723 to 27,100,777, forward strand). Ensembl gene ENSG00000138030.
Subcellular location (Human Protein Atlas): Cytosol; Vesicles
Pathways (Reactome):
Disease: Essential fructosuria
Metabolism: Fructose catabolism
Gene Ontology:
Molecular function: ATP binding; fructose binding; identical protein binding; ketohexokinase activity; protein binding; protein homodimerization activity
Biological process: fructose metabolic process; regulation of glycogen metabolic process; response to insulin
Cellular component: cytoplasm; extracellular exosome; cytosol
Genetic constraint (gnomAD): Loss-of-function variants: 36 observed, 34.91 expected, observed/expected ratio (o/e) 1.03, 90% interval 0.79 to 1.36. The upper end of that interval is the gene's LOEUF score, 1.36, which puts it in group 5 of 6, group 1 being the genes least tolerant of losing a copy. Missense variants: 395 observed, 402.11 expected, observed/expected ratio (o/e) 0.98, 90% interval 0.9 to 1.07. Synonymous variants: 161 observed, 167.63 expected, observed/expected ratio (o/e) 0.96, 90% interval 0.84 to 1.1.
Homologues: Orthologues: chimpanzee KHK (99% identical), dog KHK (88% identical), mouse Khk (87% identical), guinea pig KHK (87% identical), rat Khk (87% identical), pig KHK (73% identical), tropical clawed frog khk (71% identical), rabbit KHK (65% identical), zebrafish khk (59% identical), Drosophila melanogaster CG7328 (34% identical), Drosophila melanogaster CG7551 (34% identical), Drosophila melanogaster CG12289 (30% identical), and 1 more. Paralogues in human: RBKS (20% identical), ADK (17% identical), TMEM256 (6% identical).
Diseases named in the same sentence as KHK in open-access papers:
KHK is named in the same sentence as 54 diseases in open-access papers, as found by Europe PMC text mining. Sharing a sentence is not in itself a finding about the gene and the disease. The quoted sentences say what the papers report.
Hepatic steatosis (12 papers, 2021 to 2025). Steatosis is a term used to denote lipid accumulation within hepatocytes. "Prior in silico studies and preclinical investigations using mouse and human liver models have shown that the inhibition of KHK can reduce fructose-induced hepatic steatosis and alleviate its associated metabolic abnormalities." (PMID 40573122, 2025). "Taken together, these data demonstrate a therapeutic role for mannose in fructose-induced hepatic steatosis by dampening KHK expression." (PMID 40116750, 2025). "Studies in mice with HFD feeding with 30% fructose in drinking water for ten weeks found knockdown of KHK expression by siRNA and KHK inhibitor, PF-06835919, led to partial improvement of liver steatosis." (PMID 41196673, 2025). "The interactions between saroglitazar and ferulic acid with different enzymes and metabolites involved in metabolic dysfunction-associated fatty liver disease (MASLD), such as SORD, HK1, HK2, MgATP, KHK, HK3, ALDOB, ALDOC, and fructose-1-phosphate (F1P)." (PMID 40130107, 2025). "Both KHK siRNA and KHK inhibitor led to an improvement in liver steatosis; however, via substantially different mechanisms, KHK knockdown decreased the de novo lipogenesis pathway, whereas the inhibitor increased the fatty acid oxidation pathway." (PMID 39418102, 2024). "We show that targeting KHK via liver-specific siRNA completely and specifically prevents fructose metabolism and results in the resolution of hepatic steatosis and improves glucose tolerance." (PMID 39418102, 2024). "In summary, both KD and inhibition of KHK improved hepatic steatosis, but KHK inhibition increased liver weight, in part due to higher glycogen accumulation." (PMID 39418102, 2024). "In agreement with liver steatosis, serum triglycerides decreased in both the KHK siRNA and inhibitor groups, while serum cholesterol, which in mice mainly consists of HDL-cholesterol, was increased only in the inhibitor-treated mice." (PMID 39418102, 2024). "Overall, high glucose consumption promotes the role of KHK in fatty liver disease, metabolic disorders, and cancer, where inhibiting KHK effectively hampers the growth and movement of glioma cells in the presence of fructose." (PMID 38971308, 2024). "Secondly, hyperuricemic subjects are more prone to develop fructose-induced fatty liver, since uric acid up-regulates fructokoinase (KHK) expression in human hepatocytes, thus amplifying the lipogenic effect of fructose." (PMID 36159489, 2022). "In this sense, reduced DNL through KHK inhibition has recently emerged as a novel therapeutic approach to reduce hepatic steatosis." (PMID 35884822, 2022). "By using this model, in the present work we show that BemA treatment alleviates hepatic steatosis by several mechanisms, including reduced KHK expression, PNPLA3 induction, and PPAR⍺ activation." (PMID 35884822, 2022). "Given the central role of KHK in fructose metabolism, modulating its activity may provide a potential strategy for alleviating HFCS-induced hepatic steatosis and its associated metabolic complications." (PMID 40573122, 2025). "Additionally, knocking out KHK in mice protects against hepatic steatosis and improves insulin sensitivity." (PMID 38971308, 2024). "Both KD of KHK and inhibition of its kinase activity effectively resolve hepatic steatosis." (PMID 39418102, 2024). "The KHK inhibitor and KHK siRNA improve hepatic steatosis via different mechanisms." (PMID 39418102, 2024). "In vivo silencing of A1cf via administration of GalNAc-siRNAs reduced lipogenic gene expression and liver steatosis and phenocopied the effects of pharmacologic inhibition of KHK, making it a candidate therapeutic target for ameliorating steatosis during NASH progression." (PMID 37937648, 2023). "In this way, the SFA diet could lead to fatty liver disease and insulin resistance pathogenesis, as elevated KHK protein levels were found in liver biopsies of obese adolescent humans with NAFLD." (PMID 34063343, 2021).
Hepatic steatosis (continued). "Thus, although we could not determine the expression of intestinal KHK, we can infer from our results (reduced fructose drinking accompanied by reduced hepatic steatosis) that BemA may reduce KHK expression not only in the liver, but also in the intestine." (PMID 35884822, 2022).
metabolic syndrome (9 papers, 2013 to 2025). A cluster of metabolic risk factors for CARDIOVASCULAR DISEASES and TYPE 2 DIABETES MELLITUS. "Remarkably, the administration of osthol, a nutraceutical that has been shown to block KHK activity, resulted in the amelioration of metabolic syndrome and the prevention of kidney injury associated with inhibition of KHK expression and activity." (PMID 33670975, 2021). "These latter effects may be related to the prevention of KHK overexpression and overactivity in the liver, as the liver KHK expression appears to play a key role in driving all of the features of metabolic syndrome associated with sugar." (PMID 33670975, 2021). "Previous studies by our group propose a key role for hepatic KHK in mediating metabolic syndrome induced by fructose." (PMID 33320834, 2021). "Collectively, these studies suggest potentially protective roles of KHK suppression in metabolic syndrome." (PMID 34436420, 2021). "Another KHK isoform, namely KHK-A, is more ubiquitously expressed but has a lower affinity for fructose and as such its role in metabolic syndrome is thought to be substantially weaker." (PMID 33320834, 2021). "The significance of KHK in the fructose-induced metabolic syndrome was demonstrated in a recent study in which the syndrome was prevented in mice lacking the KHK isoforms." (PMID 24467657, 2014). "Importantly, liver-specific KHK KO mice would drink large amounts of fructose but were completely protected from both weight gain and the metabolic syndrome." (PMID 37482773, 2023). "In addition, the observed complete blockade of the metabolic syndrome in the V1bR-KO mice suggests additional mechanisms of protection beyond the upregulation of KHK." (PMID 33320834, 2021). "Based on the present knowledge of fructose and its detrimental metabolic effects when in excess and the unique nature of KHK, it is clear that fructose is, at least, partially responsible for the pandemic of diabetes and the metabolic syndrome that is presently occurring." (PMID 23762544, 2013). "In this regard, mice lacking KHK have been shown to be protected from developing metabolic syndrome by diets containing high concentrations of fructose." (PMID 33670975, 2021). "Recently, it was found that adiposity and metabolic syndrome were prevented in mice lacking both KHK isoforms but exacerbated in mice lacking KHK-A." (PMID 23762544, 2013).
steatosis (9 papers, 2016 to 2025). Increased lipid within the cytoplasm of cells. "Liver-specific deletion of A1CF in mice resulted in markedly reduced expression of these enzymes and, consequently, prevented fructose-induced hyperglycemia, hyperinsulinemia, steatosis, and adiposity, thereby phenocopying KHK deficiency in mice." (PMID 37937648, 2023). "KHK has been linked to MASLD progression; it is increased in MASH mouse models and patients, and in preclinical studies, inhibition of KHK was effective in mitigating MASH steatosis." (PMID 40116750, 2025). "We establish that mannose mitigates steatosis through decreasing KHK and that these effects are dependent on the presence of fructose." (PMID 40116750, 2025). "This study identifies mannose as a novel therapeutic candidate for MASH that mitigates steatosis by dampening hepatocyte ketohexokinase expression and exerts independent antifibrotic effects in 2 mouse models and human liver tissue slices." (PMID 40116750, 2025). "Preclinical evidence using human livers, KHK inhibition to improve steatosis, inflammation and fibrosis in NAFLD." (PMID 34203484, 2021). "In humans, KHK inhibition has been demonstrated to improve steatosis, ballooning degeneration, inflammation, and fibrosis in the liver." (PMID 34203484, 2021). "When KHK expression was inhibited by 50%, an effective reduction in lipid deposition occurred alleviating simple steatosis while fully inhibited KHK expression induced a notable decrease in lipid accumulation." (PMID 32775322, 2020). "The up-regulation of KHK was demonstrated in mice fed with a high-fat diet and correlates with steatosis and obesity: for this reason, it has been proposed as an early marker of obesity." (PMID 27713773, 2016). "If mannose attenuates steatosis through reducing KHK, we hypothesized that increasing KHK levels would negate the effects of mannose." (PMID 40116750, 2025). "Drugs targeting KHK are currently in the pipeline, including the small molecule inhibitor PF‐06835919260 and the GalNAc‐siRNA drug ALN‐KHK, which have demonstrated good efficacy (i.e., prevention of fructose‐induced hyperlipidemia, hyperinsulinemia, and steatosis)." (PMID 38344397, 2024). "Fructose is metabolized by ketohexokinase (KHK), the rate-limiting enzyme of fructolysis in both the liver and intestine; however, mouse genetic studies have suggested that only hepatic fructose catabolism drives steatosis." (PMID 37937648, 2023). "Inhibition of KHK prevents hepatic ChREBP activation by fructose in vivo and thus protects against fructose‐induced DNL, steatosis, hypertriglyceridemia and hyperinsulinemia." (PMID 38344397, 2024). "Expression profiling in livers of mice with developing steatohepatitis revealed that, at the time when livers start to accumulate lipids and develop steatosis (12 weeks of NASH diet), A1CF and KHK are induced, while TRIM21 expression starts to increase." (PMID 37937648, 2023).
diabetes (7 papers, 2013 to 2024). "Theoretically, it is plausible to test a combination therapy using AKR1B1 and KHK inhibitors to lower the risk of cancer metastasis in patients with diabetes." (PMID 38200154, 2024). "This study demonstrates the dominant role of enhanced endogenous fructose metabolism in microglia in the process of diabetes-associated cognitive dysfunction and suggests KHK as a potential therapeutic target for this condition." (PMID 37907746, 2023). "While KHK isoform choice has been linked to the development of disorders such as obesity, diabetes, cardiovascular disease and cancer, little is known about the regulation of total KHK expression." (PMID 32733884, 2020). "While the decreased prevalence of diabetes and slightly lower BMIs in participants with two KHK variants including Gly40Arg or Ala43Thr is intriguing, it should be noted these findings were not replicated in the sensitivity analysis including only white participants." (PMID 33621267, 2021). "We hypothesize that individuals either completely or partially deficient in KHK activity are immune at variable levels from developing type 2 diabetes mellitus." (PMID 23762544, 2013). "Based, in part, on the results of this study, our collaborators at Alnylam completed a phase I and are progressing with a phase II clinical trial (NCT05761301) testing KHK siRNA in patients with obesity and diabetes." (PMID 39418102, 2024). "Nonetheless, the clinical benefit observed with pharmacological inhibition suggests that KHK may be a promising therapeutic target for cardiometabolic diseases including NAFLD and type 2 diabetes mellitus." (PMID 33621267, 2021).
Obesity (7 papers, 2016 to 2024). Accumulation of substantial excess body fat. "To evaluate the role of the glucose–insulin axis in driving obesity, we administered glucose to KHK-KO mice or control mice." (PMID 37482773, 2023). "Knockdown of hepatic KHK by siRNA or combined deletion of KHK-A and KHK-C protected the mice from high fructose-induced obesity, fatty liver, glucose intolerance and insulin resistance." (PMID 33923531, 2021). "The enzyme KHK is the major mediator of metabolic outcomes of high fructose intake, and recent research has identified this enzyme as a potential therapeutic target for the management of obesity and fatty liver." (PMID 33923531, 2021). "Mice lacking KHK drank the same amount of glucose but ate less chow and while they developed mild obesity, it was approximately half that observed in the wild-type controls." (PMID 37482773, 2023). "Further support came later when we administered HFCS to mice lacking KHK and found that it provided even more protection from obesity, fatty liver and insulin resistance, with about one-quarter of the effect from the glucose–insulin pathway." (PMID 37482773, 2023).
type 2 diabetes (6 papers, 2013 to 2025). "Targeting fructose metabolism with KHK inhibitors has several potential therapeutic benefits, including treating obesity, type 2 diabetes, and fatty liver disease." (PMID 39062559, 2024). "Pharmacological inhibition of KHK also hampers the development of type 2 diabetes and NAFLD." (PMID 38971308, 2024).
glioma (4 papers, 2024 to 2025). A benign or malignant brain and spinal cord tumor that arises from glial cells (astrocytes, oligodendrocytes, ependymal cells). "KHK, a key enzyme in fructose metabolism, is involved in fructose utilization by glioma cells and promotes tumor progression." (PMID 40549205, 2025). "Glioma cells cultured in fructose medium for four weeks show upregulated KHK gene expression, increased protein stability, and upregulated KHK expression, which accelerated the malignant progression of tumors." (PMID 40549205, 2025). "Silencing KHK in glioma cells significantly inhibited their proliferation and migration." (PMID 40549205, 2025). "Therefore, novel therapeutic approaches focusing on KHK inhibition and addressing fructose intake are potential strategies for treating glioma." (PMID 38971308, 2024). "have also reported that KHK was overexpressed in glioma cells (ex." (PMID 38711514, 2024). "Taken together, both of these studies have confirmed that glioma can metabolize fructose to support its growth and migration by upregulating the expression of fructolytic enzymes, such as GLUT5 and KHK." (PMID 38711514, 2024).
Hyperglycemia (4 papers, 2017 to 2025). An increased concentration of glucose in the blood. "The deletion of KHK abolished hepatic fructose uptake and led to a dramatic hyperfructosemia, but prevented fructose-induced hyperglycemia." (PMID 28926951, 2017). "Exposure to iAs also increased SORD (sorbitol dehydrogenase), TKFC (transketolase-like protein 1), and KHK (ketohexokinase) expression in the liver, leading to increased hepatic glucose production via the polyol pathway, ultimately contributing to hyperglycemia in mice." (PMID 37886432, 2023). "After 12-weeks of ad libitum fructose feeding, there was fructose-induced hyperglycemia in wildtype mice with associated increased HbA1c levels, but not in KHK-/- mice." (PMID 28926951, 2017).
non-alcoholic fatty liver disease (4 papers, 2021 to 2025). "Fructose is transported to the liver via GLUT2 and phosphorylated by KHK in the presence of ATP to yield F-1P, which is subsequently converted to triglycerides and stored as fat; thus, high fructose consumption is also linked to nonalcoholic fatty liver disease (NAFLD)." (PMID 38971308, 2024). "In a phase 2a study (NCT03256526), administration of Pfizer’s KHK inhibitor compound (PF06835919) at doses of 75 mg or 300 mg for 6 weeks was evaluated in subjects with non-alcoholic fatty liver disease (NAFLD)." (PMID 33621267, 2021).
breast carcinoma (3 papers, 2020 to 2023). "Also, there is experimental evidence indicating that fructose can be used by breast cancer cells specifically in glucose-deficiency environments and the upregulation of KHK correlates with tumor malignancy and progression." (PMID 33425736, 2020). "In cancers such as liver and breast cancer, both KHK isoforms have been shown to have distinct roles." (PMID 37559908, 2023). "While the inborn error of KHK deficiency was described as not causing adverse effects, it has been found that in breast cancer, fructose intake induces KHK-A (ubiquitously expressed KHK isoform) entrance into the nucleus, leading to a signaling cascade triggering the metastatic phenotype." (PMID 34436420, 2021).
cardiac hypertrophy (3 papers, 2018 to 2024). "The Western diet increased fructose, uric acid, and triglyceride concentrations in cardiac tissue associated with cardiac hypertrophy, local hypoxia, oxidative stress, and increased activity and expression of KHK in cardiac tissue." (PMID 37237888, 2023). "Ketohexokinase, the central fructose-metabolizing enzyme in heart, is shown to be alternatively spliced during pathological cardiac hypertrophy by the splicing factor 3b subunit 1 (SF3B1)." (PMID 39045460, 2024). "One study also found that hypoxia-mediated cardiac hypertrophy was induced by local fructose metabolism as determined using the KHK knockout mouse." (PMID 37237888, 2023). "HIF1α activation of SF3B1-dependent splicing of KHK enforces fructolysis to promote cardiac hypertrophy in response to pathologic stress." (PMID 29695975, 2018). "HIF1α could also activate SF3B1, a splicing factor mediating isoform switch of ketohexokinase from KHK-A to KHK-C in pathologic cardiac hypertrophy." (PMID 39045460, 2024).
Insulin resistance (3 papers, 2018 to 2023). Increased resistance towards insulin, that is, diminished effectiveness of insulin in reducing blood glucose levels. "The KHK-KO mice also had minimal fatty liver or insulin resistance." (PMID 37482773, 2023).
Hypertension (2 papers, 2021). The presence of chronic increased pressure in the systemic arterial system. "Increased fructose metabolism mediated by KHK in renal tubules is associated with glomerular alterations, proteinuria, hypertension, and oxidative stress." (PMID 33670975, 2021).